ONECUT2 (one cut homeobox 2)
Description:
Transcriptional activator. Activates the transcription of a number of liver genes such as HNF3B.
Synonyms: OC-2; OC2
Tractability: No criterion of Open Targets' tractability assessment is met for any kind of drug.
Gene: Protein-coding gene on chromosome 18 (57,435,374 to 57,491,298, forward strand). Ensembl gene ENSG00000119547.
Subcellular location: Nucleus
Subcellular location (Human Protein Atlas): Nucleoplasm; Actin filaments
Gene Ontology:
Molecular function: DNA-binding transcription activator activity, RNA polymerase II-specific; RNA polymerase II cis-regulatory region sequence-specific DNA binding; sequence-specific double-stranded DNA binding; DNA-binding transcription factor activity, RNA polymerase II-specific; DNA binding; DNA-binding transcription factor activity
Biological process: positive regulation of transcription by RNA polymerase II; animal organ morphogenesis; regulation of transcription by RNA polymerase II
Cellular component: nucleoplasm; chromatin; nucleus
Genetic constraint (gnomAD): Loss-of-function variants: 10 observed, 25.06 expected, observed/expected ratio (o/e) 0.4, 90% interval 0.25 to 0.68. The upper end of that interval is the gene's LOEUF score, 0.68, which puts it in group 2 of 6, group 1 being the genes least tolerant of losing a copy. Missense variants: 684 observed, 673.63 expected, observed/expected ratio (o/e) 1.02, 90% interval 0.95 to 1.08. Synonymous variants: 326 observed, 294.01 expected, observed/expected ratio (o/e) 1.11, 90% interval 1.01 to 1.22.
Homologues: Orthologues: chimpanzee ONECUT2 (100% identical), macaque ONECUT2 (99% identical), pig ONECUT2 (99% identical), mouse Onecut2 (99% identical), dog ONECUT2 (99% identical), guinea pig ONECUT2 (88% identical), rat Onecut2 (81% identical), tropical clawed frog onecut2 (80% identical), zebrafish onecut2 (73% identical), rabbit ONECUT2 (57% identical), Drosophila melanogaster onecut (47% identical), Caenorhabditis elegans ceh-48 (39% identical), and 4 more. Paralogues in human: ONECUT1 (63% identical), ONECUT3 (53% identical).
Diseases named in the same sentence as ONECUT2 in open-access papers:
ONECUT2 is named in the same sentence as 55 diseases in open-access papers, as found by Europe PMC text mining. Sharing a sentence is not in itself a finding about the gene and the disease. The quoted sentences say what the papers report.
prostate carcinoma (15 papers, 2019 to 2026). A carcinoma that arises from epithelial cells of the prostate gland. "In 208 biopsies from prostate cancer patients, hypermethylation of gene-body of ONECUT2 was linked to higher ONECUT2 expression and effectively distinguished tumor from adjacent normal tissue (p < 0.001 and AUC = 0.86)." (PMID 41545903, 2026). "Specifically in prostate cancer, increased ONECUT2 expression has been linked to the aggressiveness of the disease, disease progression, biochemical recurrence, and metastasis." (PMID 35582526, 2022). "ONECUT2 target genes are involved in the cell cycle, angiogenesis, and hypoxia, which in turn are implicated in tumor growth and metastasis in prostate cancer." (PMID 35582526, 2022). "Our study demonstrates a strong association between ONECUT2 gene-body DNA methylation and aggressive prostate cancer features, validated using public Illumina Infinium methylation datasets as well as targeted bisulfite sequencing and qRT-PCR in our needle biopsy cohort." (PMID 41545903, 2026). "The effect of DNA methylation on ONECUT2 expression was tested in prostate cancer cell lines using a DNA methyltransferase inhibitor (DNMTi)." (PMID 41545903, 2026). "Base interactions by this ONECUT family-specific arginine pair as well as the evolutionarily conserved residues are critical for optimal DNA binding and ONECUT2 transcriptional activity in a prostate cancer model." (PMID 39426953, 2024). "In prostate cancer, ONECUT2 operates as an oncogene by activating expression of SMAD3 which regulates tumor growth under hypoxic conditions." (PMID 38474011, 2024). "Here, the authors use an integrative approach to study the mechanism of CUT-HOX cross-talk towards DNA binding by the prostate cancer target ONECUT2." (PMID 39426953, 2024). "In prostate cancer, ectopic ONECUT2 expression, in conjunction with hypoxia, inhibits androgen signaling and induces neuroendocrine plasticity, thereby promoting prostate neuroendocrine cell proliferation." (PMID 38997271, 2024). "ONECUT2 represents the first-described dual-modality transcript that operates as both a key transcription factor driving castration-resistant prostate cancer and a master ceRNA that promotes and protects the same transcriptional network." (PMID 37484909, 2023). "The transcription factor ONECUT2 (OC2) is a master transcriptional regulator operating in metastatic castration-resistant prostate cancer that suppresses androgen receptor activity and promotes neural differentiation and tumor cell survival." (PMID 37484909, 2023). "In contrast to ONECUT1, ONECUT2 expression has been shown to be elevated in multiple different cancers, including prostate cancer, ovarian cancer, gastric cancer, colorectal cancer, hepatocellular carcinoma, lung adenocarcinoma, and neuroendocrine tumors." (PMID 35582526, 2022). "High expression of ONECUT2 and PRSS21 have been reported to be associated with poorer prognosis in various cancers including prostate cancer, hepatocellular carcinoma, and gastric cancer." (PMID 35754804, 2022). "Taken together, the experimental data available demonstrate that ONECUT2 is a key player in prostate cancer progression into its most aggressive form, NEPC." (PMID 33572108, 2021). "The importance of ONECUT2 in prostate cancer progression has been recently recognized and its role in NEPC has been further elucidated." (PMID 33572108, 2021). "Here, we demonstrated a robust positive correlation between ONECUT2 gene-body DNA methylation and gene expression across several public databases, which we also confirmed this correlation not only in prostate cancer cell lines but also the key clinic specimen, needle biopsy before the surgery." (PMID 41545903, 2026). "ONECUT2 is a lineage plasticity driver and therapeutic target in aggressive prostate cancer (PCa)." (PMID 41545903, 2026). "Notably, the treatment response to CSRM617 exhibited a direct correlation with ONECUT2 expression in prostate cancer cell lines." (PMID 41545903, 2026).
prostate carcinoma (continued). "SMAD3 reportedly supports the growth of prostate cancer cells under hypoxic conditions, further supporting the notion that hypoxic adaptation may represent an important oncogenic function of ONECUT2 and its target genes SMAD3 and EPAS1 in BPDCN." (PMID 38474011, 2024). "ONECUT2 has been shown to play a role in NE differentiation in prostate cancer." (PMID 35582526, 2022). "Altogether, these findings show that ONECUT2 leads to AR independence in prostate cancer." (PMID 35582526, 2022). "The investigators further showed that CSRM617 can inhibit cell growth and induce apoptosis in vitro in several prostate cancer cell lines that express moderate to high levels of ONECUT2 and that the compound can suppress prostate cancer growth and metastasis in a nude mouse model system." (PMID 30866492, 2019). "Treatment of prostate cancer with AR inhibition may lead to selection for cancer cells with elevated ONECUT2 expression, thereby contributing to resistance to AR-targeted therapy and development of NE features that lead to more aggressive phenotypes with worse clinical outcomes." (PMID 35582526, 2022). "ONECUT2 activates SMAD3 and EPAS1 which mediate survival of tumor cells under hypoxic conditions as shown recently for SMAD3 in prostate cancer and in this study for EPAS1 in BPDCN." (PMID 38474011, 2024). "Using ONECUT2, a driver and therapeutic target of advanced prostate cancer, we show that while the CUT initiates DNA binding, the homeodomain thermodynamically stabilizes the ONECUT2-DNA complex through allosteric modulation of CUT." (PMID 39426953, 2024). "ONECUT2 modulates the expression of oncogenic lncRNA PCAT1 in prostate cancer, indicating its potential role in prostate cancer development." (PMID 30655535, 2019). "ONECUT1 and ONECUT2 have been reported in tumors: highly active ONECUT1 can suppress the proliferation and metastasis of colorectal and lung cancer cells, whereas ONECUT2 acts as a survival factor and a driver of prostate cancer." (PMID 38386414, 2024).
breast carcinoma (10 papers, 2015 to 2025). "In breast cancer, ONECUT2 inhibits CASP3 and activates BCL2, which together support survival of these tumor cells." (PMID 38474011, 2024). "Following chemotherapy for breast cancer, ONECUT2 induces tumor stemness and triggers the expression of stem cell-related genes, including SOX9, SOX2, and NOTCH1, thereby contributing to chemoresistance." (PMID 38997271, 2024). "In contrast, levels of ONECUT2 were found to be lower in breast cancer, and patients with low expression levels showed worse survival than those with high expression levels of ONECUT2." (PMID 36140249, 2022). "The cyclic Arg-Gly-Asp (cRGD) modified cationic liposomes (cRGD-CL) were designed for targeted delivery of ONECUT2 (OC-2) shRNA (pshOC-2) to breast cancer cells." (PMID 36297592, 2022). "MiR-9-5p, miR-195-5p, and miR-203a-3p carried by exosomes all target One Cut Homeobox 2 (ONECUT2) to enhance the stemness of breast cancer." (PMID 33579377, 2021). "We selected ERBB2, GRB7 and ONECUT2 for validation due to their importance in the biology of breast cancer, the magnitude of the change found in the RNA-seq data analysis and the consistency between the European and IA ancestry analyses." (PMID 28832682, 2017). "Among these genes, AP3B1, ONECUT2 and IL-6 were already confirmed to be direct targets of miR-9 in breast cancer, insulin-producing cells, and cervical adenocarcinoma, respectively, which demonstrated the reliability of our screening strategy." (PMID 26547929, 2015).
colorectal cancer (9 papers, 2014 to 2024). A primary or metastatic malignant neoplasm that affects the colon or rectum. "ONECUT2 has been implicated in the regulation of epithelial-mesenchymal transition (in colorectal cancer) by controlling the expression of E-cadherin and vimentin, thereby enhancing colorectal cancer cell invasiveness and metastatic potential." (PMID 38997271, 2024). "Conversely, the overexpression of ONECUT 2 in colorectal cancer cells rescued them from the proliferation loss both under miR-296-3p overexpression or lncRNA-XLOC_006390 silencing." (PMID 35874630, 2022). "The results of the current study pointed out that colorectal cancer is linked with high ONECUT 2 expressions resulting from miR-296-3p downregulation which in turn emerges from the sponging action of lncRNA-XLOC_006390." (PMID 35874630, 2022). "Increased expression of the transcription factor one-cut domain 2 (ONECUT2) has been observed in various cancers, including colorectal cancer, which is associated with tumor growth, metastasis, chemoresistance, and poor prognosis and is considered a potential therapeutic target in CRC." (PMID 39028420, 2024). "LncRNA-XLOC_006390 was shown to sponge the expression of miR-296-3p which in turn acted via post-transcriptional suppression of ONECUT 2 transcription factor to regulate the growth of colorectal cancer." (PMID 35874630, 2022). "Taken together, the results revealed the oncogenic role of lncRNA-XLOC_006390 in colorectal cancer via modulation of miR-296/ONECUT2 axis." (PMID 35874630, 2022). "Nonetheless, the molecular role of lncRNA-XLOC_006390 in colorectal cancer via modulation of miR-296/ONECUT2 axis is still unclear." (PMID 35874630, 2022). "ONECUT 2 is a homeodomain type of transcription factor whose expressional elevation promotes the growth and metastasis of colorectal cancer cells." (PMID 35874630, 2022). "The present study thus indicated that the enhancement in miR-296 sponging by lncRNA-XLOC_006390, due to overexpression in colorectal cancer, alleviates posttranscriptional targeting of ONECUT 2, and the latter promotes the cancer growth and proliferation." (PMID 35874630, 2022). "Transcriptional repression of ONECUT 2 in CaCo2 colorectal cancer cells declined the cell proliferation significantly (P < 0.05)." (PMID 35874630, 2022). "The results showed that lncRNA-XLOC_006390 silencing induces apoptosis of colorectal cancer cells via modulation of miR-296/ONECUT 2 axis." (PMID 35874630, 2022). "Taken together, the results suggest that lncRNA-XLOC_006390 executes its regulatory role in colorectal cancer through miR-296/ONECUT 2 regulatory axis." (PMID 35874630, 2022). "Moreover, EIF4A3-induced circ_0084615 promoted colorectal cancer proliferation, migration, and invasion via the miR-599/ONECUT2 axis." (PMID 37322413, 2023). "miR-429 inhibits cells invasion by targeting Onecut2 in colorectal carcinoma." (PMID 25405387, 2015).
gastric cancer (8 papers, 2020 to 2026). A primary or metastatic malignant neoplasm involving the stomach. "YTHDF2 is downregulated, and its overexpression facilitates ONECUT2 mRNA degradation through m6A modification in gastric cancer." (PMID 40986143, 2025). "We found that high expression of CPVL, ONECUT2, DDC, PRSS21, and GRTP1 increase the risk of gastric cancer." (PMID 35754804, 2022). "Importantly, YTHDF2-mediated m6A modification of one cut homeobox 2 (ONECUT2) can promote stemness in gastric cancer." (PMID 40986143, 2025). "Esophageal cancer patients with high expression of FOXN1, GRHL3, and HES2, stomach cancer patients with high expression of ONECUT2, thyroid cancer patients with high expression of PAX8, and uterine cancer patients that expressed elevated levels of MECOM had decreased survival." (PMID 37627195, 2023). "The high risk-scores of CPVL, ONECUT2, DDC, PRSS21, and GRTP1 could be used to determine the degree of malignancy and prognosis in gastric cancer patients." (PMID 35754804, 2022). "This study explored ONECUT2’s role and the specific mechanism underlying HP infection-associated gastric carcinogenesis to suggest a basis for targeting ONECUT2 as a therapeutic strategy for gastric cancer (GC)." (PMID 38997271, 2024). "To find out the role of hub genes in the overall survival of gastric cancer we performed a multivariate Cox regression analysis, among 21 hub genes, the eight genes (KCNJ3, CPVL, ONECUT2, SLC19A3, DDC, PRSS21, F12, and GRTP1) were designated as independent indicators of poor prognosis." (PMID 35754804, 2022). "The m6A reader protein YTHDF2 mediates the m6A modification of ONECUT2 mRNA, thereby activating TFPI transcription, leading to stemness in gastric cancer and resistance to oxaliplatin, providing a new treatment target to tackle gastric cancer that is resistant to oxaliplatin." (PMID 41584846, 2025).
lung carcinoma (8 papers, 2019 to 2025). "We chose A549, a human lung adenocarcinoma cell line with homozygous KRASG12S mutation, to investigate the role of ONECUT2 in lung cancer progression." (PMID 31882655, 2019). "In lung cancer, ONECUT2 promotes stem cell properties and affects the progression of RAS-driven tumors." (PMID 38997271, 2024). "The aberrant expression of ONECUT2 has been reported in prostate and lung cancer, demonstrating the oncogenic potential of this factor when deregulated." (PMID 38474011, 2024). "ONECUT2 activates distinct gene expression profiles by promoting the trans-differentiation of lung cancer cells by modulating Polycomb Repressive Complex 2 (PRC2) occupancy of distinct chromatin domains." (PMID 32046099, 2020). "One cut homeobox 2 (ONECUT2), a transcription factor, is highly overexpressed in a number of human malignancies including prostate and lung cancer." (PMID 32046099, 2020). "We first analyzed ONECUT2 expression across various subtypes of lung cancer using publicly available dataset GSE3021920." (PMID 31882655, 2019). "ONECUT2 overexpression promoted the malignant growth and invasion of A549 lung cancer cells in vitro, as well as xenograft tumorigenesis and bone metastases of these cells in vivo." (PMID 31882655, 2019). "Overall, we concluded that overexpression of ONECUT2 promoted the malignant growth, migration, invasion and adhesion of A549 lung cancer cells." (PMID 31882655, 2019). "Here, we report ectopic activation of the hepatobiliary-, intestinal- and neural-specific gene one cut homeobox 2 (ONECUT2) in various subtypes of lung cancer." (PMID 31882655, 2019). "In contrast, ONECUT2 acts as an oncogene in prostate and lung cancer." (PMID 38474011, 2024). "Integrative transcriptomics and epigenomics analyses suggested that ONECUT2 promoted the trans-differentiation of lung cancer cells by preferentially targeting and regulating the activity of bivalent chromatin domains through modulating Polycomb Repressive Complex 2 (PRC2) occupancy." (PMID 31882655, 2019). "Moreover, consistent with the lineage-restricted expression pattern of ONECUT2, ONECUT2 activated genes specifically expressed in neural, hepatobiliary and intestinal tissues, suggesting the activation of trans-differentiation programs in ONECUT2-overexpressed lung cancer cells." (PMID 31882655, 2019). "However, the role of ONECUT2 in lung cancer progression is unknown." (PMID 31882655, 2019). "Targeted manipulation of histone methylation orchestrated by the oncogenic transcriptional regulation of ONECUT2 contributes to the epigenetic reprogramming, aggressive behavior and metastasis of RAS-driven lung cancer." (PMID 31882655, 2019). "ONECUT2, also known as One Cut Homeobox 2 (ENSG00000119547), is a transcription factor that upregulates cell proliferation, migration, adhesion, and differentiation processes in several tumors, including prostate, colorectal, ovarian, and lung cancer." (PMID 40863726, 2025). "Besides SCLC, LCNEC and carcinoid, ONECUT2 was also highly expressed in a subset of lung adenocarcinoma (ADC), the most frequent subtype of lung cancer." (PMID 31882655, 2019). "Indeed, our analysis showed that ONECUT2 expression was elevated specifically, in poorly differentiated lung cancers and nervous system NETs compared with non-NETs." (PMID 30655535, 2019).